APOA1 (apolipoprotein A1)
Diseases named in the same sentence as APOA1 in open-access papers (continued):
Sharing a sentence is not in itself a finding about the gene and the disease.
atherosclerosis (continued). "ApoB/ApoA1 is a balance index reflecting antiatherosclerotic lipoprotein and promoting atherosclerosis in the plasma." (PMID 37063111, 2023). "During atherosclerosis, apolipoprotein A1 (ApoA1) indirectly affects T cell responses during inflammation." (PMID 38143759, 2023). "Going beyond conventional lipid-lowering drugs, ApoA-1 mimetics, which enhance cholesterol efflux, have been receiving attention regarding inhibition of atherosclerosis progression." (PMID 36671490, 2023). "The volume of atherosclerosis lesions was decreased substantially by approximately 50% as a result of the apoA1 Milano “rice milk” therapy; in mice fed with natural rice milk, there was no such effect." (PMID 36979690, 2023). "The atherosclerosis of the aorta was decreased by 25% with the apoA1 gene of wild type, which is 65% lower than the effect of apoA1 Milano." (PMID 36979690, 2023). "The activity of oxidant resistant human apoA1 was compared to unmodified human apoA1 in mouse models of atherosclerosis progression and regression." (PMID 35120132, 2022). "On the contrary, apoA1, a major protein component of high-density lipoprotein cholesterol (HDL-C) is strongly and inversely correlated to the risk of atherosclerosis and progression of vascular diseases." (PMID 35525960, 2022). "Molecular research in diabetic mice, as well as clinical trials including diabetic individuals have proven that apoA1 promotes atherosclerosis regression, while decreased levels of this biomarker are blamed for increased incidence of atherosclerotic disease." (PMID 35525960, 2022). "Animal models have proven the RCT pathway and that increases in macrophage-to-feces cholesterol delivery, such as in apoA1 transgenic mice, leads to decreased atherosclerosis progression." (PMID 35052806, 2022). "As the main component of HDL-C, apolipoprotein A1 has a protective effect against atherosclerosis and inflammation." (PMID 36615770, 2022). "Transgenic overexpression of apolipoprotein A-I (apoA1) has been shown to delay atherosclerosis lesion progression and promote lesion regression in mouse models; however, apoA1 is subject to oxidation by myeloperoxidase (MPO) and loss of function." (PMID 35120132, 2022). "Patients with high ApoB:ApoA1 ratio shared a serum metabolomic profile with adult SLE patients with sub-clinical atherosclerosis; a CD8+ T-cell phenotype with CD8+ T-cells isolated from human atherosclerotic plaque; and had a more active disease trajectory." (PMID 33640328, 2021). "Therapeutic approaches inspired by ApoA1 have been developed primarily to increase levels of ApoA1 in order to treat atherosclerosis and acute coronary syndrome." (PMID 32456156, 2020). "The present study reveals that atherosclerosis-lupus-prone mice develop vulnerable atherosclerotic plaques in correlation with the production of anti-ApoA-1 IgG and anti-dsDNA IgG antibody levels, both known to have critical pro-atherosclerotic activity." (PMID 33110193, 2020). "Somatic gene transfer of human APOA1 reduced atherosclerosis progression in human APOA1-transgenic mice and ApoE−/− mice." (PMID 32566106, 2020). "Apolipoprotein A1, a biomarker for subclinical atherosclerosis, was also found to be inversely related to T levels." (PMID 32881896, 2020). "Apolipoprotein B, which is a component of LDL-C and TG, contributes to atherogenesis, although the protective role of HDL-C, which mainly includes apolipoprotein A1, on atherosclerosis has been described." (PMID 32752179, 2020). "One of the potential biomarkers of atherosclerosis analyzed in this work is ApoA1, the major protein constituent of the plasma HDL complex." (PMID 33086557, 2020). "SAA has also been associated with the increased prevalence of atherosclerosis in sarcoidosis patients by lowering serum levels of HDL and apoA1." (PMID 31681260, 2019). "This is the first report of the presence of an emerging biomarker for atherosclerosis, anti-apoA-1 IgG, in some patients with HCV infection." (PMID 29423541, 2018).
atherosclerosis (continued). "For example, in patients with periodontitis, where it is a biomarker of atherosclerosis burden, the prevalence of anti-apoA-1 IgG was found to be 23.8% compared to 6.5% in age- and sex-matched controls (p = 0.009)." (PMID 29423541, 2018). "Increased PON1 and APOA1 in SO/SOAE pre-treated animals suggests enhanced functionality of HDL as well as protection against oxidative stress-induced atherosclerosis." (PMID 30115989, 2018). "ApoA-I or ApoA-1 mimetics reduced or regressed atherosclerosis in animals, altering HDL function (e.g., inhibiting LDL oxidation) without changing HDLc mass." (PMID 29099757, 2017). "Taking into consideration these studies, in the present study we examined the dose-dependent effects of caffeine on liver PON1, PON3 and ApoA1 protein levels, and we evaluated a possible relationship between caffeine and atherosclerosis." (PMID 29215336, 2017). "Not surprisingly, the documented number of “proinflammatory monocytes” was a much stronger predictor of atherosclerosis-related complications compared with HDL cholesterol or apoA1 concentrations." (PMID 27481939, 2016). "Many studies have proven that defects in ABCA1 impaired apoA-1-mediated intercellular lipid efflux in early atherosclerosis." (PMID 25601961, 2015). "ApoB/apoA1 ratio has also been shown to be a good predictor of cardiovascular disease and atherosclerosis, and it has been suggested that ApoB/apoA1 ratio should be used instead of cholesterol concentrations as a risk marker of myocardial infarction." (PMID 25000408, 2014). "Plasma apoA1 and apoB levels are stronger predictors of premature atherosclerosis than other plasma lipoproteins." (PMID 22811893, 2012). "Serum amyloid A protein (SAA) is not only an inflammatory factor, but also an apolipoprotein that can replace apolipoprotein A1 (apoA1) as the major apolipoprotein of high-density lipoprotein (HDL), which has been linked to atherosclerosis." (PMID 21103356, 2010). "Animal studies have shown that the presence of both transgenic apo(a) plus apoA1 results in animals protected against diet-induced atherosclerosis." (PMID 17683612, 2007). "Blockade of APOA1 cleavage by AEP diminishes atherosclerosis in APOE–/– mice." (PMID 40371638, 2025). "Furthermore, some studies have suggested that the ApoB–apolipoprotein A1 (ApoA1) ratio has a higher predictive value for atherosclerosis and intima-media thickness than individual lipid markers." (PMID 39851250, 2025). "The protective effect of apoA1 is attributed to its crucial role in cholesterol metabolism and HDL synthesis, as well as its involvement in regulating inflammatory and immune responses associated with atherosclerosis, amyloidosis, and cardiovascular diseases." (PMID 41567545, 2025). "Both the expression of ATP-binding cassette transporter A1 (ABCA1) and its binding to apolipoprotein A-I (ApoA1) of high-density lipoproteins (HDLs) are reduced in human SMCs, with this impairment appearing to be more pronounced in the advanced stages of atherosclerosis." (PMID 38952543, 2024). "Perhaps in the progression of CHB disease, HBV reduces the risk of atherosclerosis through the incompletely verified molecular mechanism, resulting in a negative correlation between ApoB/ApoA1 ratio and the prevalence of HCC and LC." (PMID 38744926, 2024). "This was supported by disease-wise association analysis in our study using data from the UK Biobank, which showed a strong and significant association between the ApoA1 and HDL-subset signature (reduced levels) and increased risk of atherosclerosis and mortality from myocardial infarction." (PMID 38048621, 2024).
atherosclerosis (continued). "In addition, the increase of HDL/ApoA1 in plasma can prevent the progression of diabetes, nervous system disease, and inflammation, as well as play a protective role in atherosclerosis and related cardiovascular diseases." (PMID 38357546, 2024). "AVAS-induced inhibition of peripheral cholesterol esterification was originally a therapeutic target for atherosclerosis as it facilitated cholesterol efflux to apoA1-HDL in plasma, thus reducing the development of foam cells from macrophage uptake of oxidized LDL." (PMID 37157042, 2023). "Moreover, the SDF-1/CXCR4 interaction inhibits the ABCA1-dependent cholesterol efflux from macrophages to apolipoprotein A1 (ApoA1) thus aggravating the atherosclerosis." (PMID 37894988, 2023). "HDL is involved in the reverse transport of cholesterol (as a vascular protective factor that has an anti-atherosclerosis effect while ApoA1 is a tool to carry HDL), is also a component of HDL, and has a relatively important role in preventing the occurrence of atherosclerosis." (PMID 37629504, 2023). "It is stated in an accompanying Editorial that the results of apoA1 Milano administration in stable and acute atherosclerosis might vary, showing positive results in the former case." (PMID 36979690, 2023). "Furthermore, HDL-C is a highly heterogeneous class of lipoproteins, the main members of which are ApoA1 and ApoA2, which have major antioxidant and anti-inflammatory properties that effectively prevent atherosclerosis." (PMID 38155948, 2023). "Wang and colleagues were the first to study the assumption that apoA1 Milano gene therapy may appear more efficient in atherosclerosis treatment than the standard administration of recombinant apoA1 Milano." (PMID 36979690, 2023). "Liver-derived apolipoprotein A1 (APOA1) is the primary protein constituent of HDL particles and, as a result, genetic APOA1 deficiency is associated with isolated HDL deficiency and a high predisposition for the development of atherosclerosis in humans." (PMID 34698355, 2022). "ApoA-1 decreased plaque inflammation and atherosclerosis in diabetic mice." (PMID 36619946, 2022). "The relatively high blood lymphocyte concentrations observed in LDL receptor KO mice after transplantation with bone marrow from APOA1 KO mice did not constitute a change in atherosclerosis susceptibility." (PMID 34698355, 2022). "As inflammation and oxidative stress play central roles not only in atherosclerosis, but also in the carcinogenesis of various cancers, the association between decreased HDL or ApoA1 and increased risk of cancer has been indicated through the dysfunction of such beneficial properties." (PMID 35796324, 2022). "APOA1 or APOA2 deficiency can cause hypertriglyceridemia and in the long-term atherosclerosis." (PMID 36189295, 2022). "Due to the inverse association of HDL-C with CHD, and the proven effect of apoA1 overexpression decreasing atherosclerosis progression in mouse models, apoA1, reconstituted HDL (rHDL), or apoA1 mimetic peptides have been utilized in multiple pre-clinical and clinical trials." (PMID 35052806, 2022). "ApoA1 is reported to regulate the expression of apolipoprotein in brain and reduce atherosclerosis." (PMID 34295249, 2021).
atherosclerosis (continued). "Because chemokines and chemokine receptors are critical in the development of atherosclerosis, modulation of their expression by ApoA1 suggest that low ApoA1 levels may allow increased monocyte recruitment." (PMID 33717107, 2021). "In this comprehensive analysis of >220 serum biomarkers in patients with JSLE who mostly had normal total cholesterol and triglyceride levels, apoB:apoA1 was also identified as a marker correlating with elevated metabolites in adult patients of SLE with atherosclerosis." (PMID 33774330, 2021). "On the other hand, peroxidized fatty acids have also been shown to increase the expression of apolipoprotein A1 (ApoA1), a component of the lipoprotein complex generally believed to provide some level of protection against atherosclerosis, high-density lipoprotein (HDL)." (PMID 34439506, 2021). "Animal studies have also shown that APOA1 inhibits the progression of atherosclerosis." (PMID 32566106, 2020). "We were unable to find any similar studies in the literature showing that the immune response against HDL induces atherosclerosis, except for the fact that in patients the titer of circulating ApoA1‐reactive IgG antibodies is a superior predictor of major cardiac events." (PMID 32790236, 2020). "The main plasma risk factors that promote the development of atherosclerosis are elevated low-density lipoprotein (LDL) cholesterol level, low high-density lipoprotein (HDL) level, lipidogram disorders, as well as low level of ApoA1." (PMID 33086557, 2020). "Finally, we detected that plasma CCDC80 level was positively associated with the dyslipidemia and atherosclerosis marker LDL-C, apoA1 and apoB." (PMID 31992220, 2020). "Several studies have identified ApoA1 as a key determinant of macrophage cholesterol efflux capacity, ApoA1 proteins may reduce atherosclerosis via regulating cholesterol efflux from macrophages." (PMID 31391051, 2019). "Integrative interpretation of a subset of measures, e.g., cIMT, CRP, and sICAM-1, and calculation of the ApoB100/ApoA1 ratio might help in the early estimation of premature atherosclerosis in psoriatic patients." (PMID 29535705, 2018). "Therefore, HDL and ApoA1 as the main constituents of HDL are very important to prevent cardiovascular disease such as atherosclerosis, which is result of accumulation of extra cholesterol in the blood." (PMID 28695482, 2017). "ApoA1 is an important activator of LCAT, and modified ApoA1 may compromise RCT and cause atherosclerosis." (PMID 26090384, 2015). "It has been suggested that anti-apoA-1 could interfere with this protective effect and thus promote atherosclerosis." (PMID 25890187, 2015). "In addition to cholesterol efflux, ApoA1 possesses anti-inflammatory and antioxidative properties, and ApoA1 mimetics are an effective treatment for atherosclerosis and several inflammatory disorders in animal models." (PMID 23409054, 2013). "Thus for primordial and primary prevention of atherosclerosis, we suggest screening these children for low plasma apoA1 and high plasma apoB levels." (PMID 22811893, 2012). "Because of the beginning of the atherosclerosis' process from early life, in this study, the plasma levels of apoA1 and apoB were compared in diabetic children with type I diabetes mellitus(DM), healthy children with diabetic parents (HDPs),and healthy children with nondiabetic parents (HNDPs)." (PMID 22811893, 2012). "However, the effect of ApoA1 deficiency on macrophage apoptosis during atherosclerosis development in vivo has not been fully explored." (PMID 40120762, 2025). "The absence of suitable prophylaxes for atherosclerosis risk in both terrestrial humans exposed to radiation and astronauts exposed to space radiation motivates the thorough analysis of the APOA1 R173C mechanism to potentially uncover safe and effective therapeutic compounds." (PMID 39039045, 2024). "Thus, HDL and ApoA1 could be more relevant players in the mechanisms of premature atherosclerosis due to SLE disease itself." (PMID 38048621, 2024).
atherosclerosis (continued). "Several studies have demonstrated that ApoA1 exerts regulatory effects on cholesterol levels, IL-2 receptor expression, and IL-6 expression in Treg cells during the progression of atherosclerosis, thereby impeding the transition from exTregs to Tfh cells and ultimately reducing atherosclerosis." (PMID 38143759, 2023). "Furthermore, studies have found that the cardiovascular drug perhexiline can induce the expression of KLF14 and increase blood HDL-C levels and cholesterol outflow ability by upregulating ApoA1 and ameliorating the development of atherosclerosis by targeting the KLF14 pathway." (PMID 34983946, 2022). "We identified the ApoB:ApoA1 ratio as a potential predictive biomarker of increased CVD risk in patients, who shared a serum metabolomic profile with adult SLE patients with sub-clinical atherosclerosis and a T-cell phenotype with T-cells isolated from human atherosclerotic plaque." (PMID 35050125, 2021). "Therefore, RIPK1i might reduce HDL via inhibition of liver synthesis of ApoA1, contributing to the pathogenesis of atherosclerosis at a later stage." (PMID 34760938, 2021). "Auto-antibodies against apoA-1 (anti-apoA-1 IgGs) have been identified as important actors of atherosclerosis development through pro-inflammatory and pro-atherogenic properties and to also induce apoptosis in tumoral neuronal and lymphocyte derived cell lines through unknown mechanisms." (PMID 33245719, 2020). "The increase of ApoB or decrease of apoA1 indicates the increase of cholesterol transport to peripheral tissues or decrease of cholesterol transport back to liver, leading to more cholesterol deposition on the blood vessel wall and promoting the occurrence of atherosclerosis (AS)." (PMID 32539722, 2020). "Unlike the protective effect of ApoA1 on atherosclerosis, the serum ApoA1 was associated with arterial stiffness in male NAFLD patients, suggesting that NAFLD may alter arterial stiffness by “ApoA1-related” mechanism in male NAFLD population." (PMID 32874784, 2020). "Therefore, increased ApoB/ApoA1 ratio exacerbating the atherosclerosis and inflammation of intracranial vascular might explain our findings of a correlation of the ApoB/ApoA1 ratio with RN volume." (PMID 32017458, 2020). "Since the SNPs at 11q23.3 region harbouring apolipoprotein coding genes namely APOA1, APOC3, APOA4, APOA5 and regulatory genes BUD13, ZPR1, SIK3 were found to be associated with defective lipid metabolism, this region was thought to play an important role in atherosclerosis and CAD risk." (PMID 33298998, 2020). "Blockade of APOA1 cleavage by AEP inhibitor #11a or by overexpressing the uncleavable APOA1 N208A mutant increases HDL-C levels and delays atherosclerosis progression." (PMID 40371638, 2025). "Through these functions, ApoA1-rich HDL particles can extract cholesterol from plaque-laden macrophages in arteries and therefore protect against atherosclerosis." (PMID 40944180, 2025). "Here, we show that AEP is augmented in the atherosclerosis plaques obtained from patients and proteolytically cuts apolipoprotein A1 (APOA1) and impairs cholesterol efflux and high-density lipoprotein (HDL) formation, facilitating atherosclerosis pathologies." (PMID 40371638, 2025). "In the current work, we show that AEP cleaves APOA1, a major component in HDL, diminishes cholesterol clearance, facilitating atherosclerosis onset." (PMID 40371638, 2025). "Apolipoprotein A1 (ApoA1), the main component of HDL, has been extensively studied in the context of atherosclerosis, thrombotic diseases, diabetes, and nervous system diseases." (PMID 38212711, 2024). "In contrast, apolipoprotein A1 (Apo-A1), the major lipoprotein component of plasma high-density lipoprotein (HDL), is protective against atherosclerosis." (PMID 39432657, 2024).